NEUROG1 (neurogenin 1)
Description:
Acts as a transcriptional regulator. Involved in the initiation of neuronal differentiation. Activates transcription by binding to the E box (5'-CANNTG-3'). Associates with chromatin to enhancer regulatory elements in genes encoding key transcriptional regulators of neurogenesis (By similarity).
Synonyms: bHLHa6; NeuroD3; NGN1; AKA; Math4C; CCDDRD
Tractability: No criterion of Open Targets' tractability assessment is met for any kind of drug.
Gene: Protein-coding gene on chromosome 5 (135,534,282 to 135,535,964, reverse strand). Ensembl gene ENSG00000181965.
Subcellular location: Nucleus
Subcellular location (Human Protein Atlas): Nucleoplasm; Nuclear bodies
Gene Ontology:
Molecular function: DNA binding; E-box binding; protein binding; protein homodimerization activity; sequence-specific double-stranded DNA binding; chromatin binding; DNA-binding transcription factor activity; DNA-binding transcription factor activity, RNA polymerase II-specific; protein dimerization activity
Biological process: auditory behavior; cochlea development; cochlea morphogenesis; craniofacial suture morphogenesis; genitalia development; genitalia morphogenesis; hard palate morphogenesis; inner ear development; inner ear morphogenesis; learned vocalization behavior; mastication; negative regulation of relaxation of muscle; negative regulation of saliva secretion; neuromuscular process controlling balance; peristalsis; regulation of muscle organ development; thorax and anterior abdomen determination; trigeminal nerve development; vestibulocochlear nerve formation; axon development; forebrain development; nervous system development; positive regulation of neuron differentiation; positive regulation of transcription by RNA polymerase II; regulation of transcription by RNA polymerase II; and 1 more
Cellular component: chromatin; nucleus; neuronal cell body; perikaryon
Genetic constraint (gnomAD): Loss-of-function variants: 9 observed, 8.12 expected, observed/expected ratio (o/e) 1.11, 90% interval 0.66 to 1.79. That is too few expected variants to judge how well the gene tolerates losing a copy. Missense variants: 403 observed, 342.78 expected, observed/expected ratio (o/e) 1.18, 90% interval 1.08 to 1.28. Synonymous variants: 196 observed, 152.87 expected, observed/expected ratio (o/e) 1.28, 90% interval 1.14 to 1.44.
Homologues: Orthologues: chimpanzee NEUROG1 (99% identical), macaque NEUROG1 (96% identical), pig NEUROG1 (90% identical), mouse Neurog1 (89% identical), rat Neurog1 (89% identical), dog NEUROG1 (88% identical), guinea pig NEUROG1 (88% identical), tropical clawed frog neurog1 (45% identical), Drosophila melanogaster tap (32% identical), Caenorhabditis elegans ngn-1 (23% identical), Drosophila melanogaster ato (16% identical), Caenorhabditis elegans lin-32 (15% identical), and 1 more. Paralogues in human: NEUROG2 (38% identical), NEUROG3 (35% identical), NEUROD6 (30% identical), NEUROD1 (29% identical), NEUROD4 (27% identical), NEUROD2 (27% identical), ATOH1 (22% identical), BHLHA15 (21% identical), ATOH8 (19% identical), BHLHE23 (19% identical), OLIG3 (18% identical), ATOH7 (18% identical), and 3 more.